C2 (complement C2)
Description:
Precursor of the catalytic component of the C3 and C5 convertase complexes, which are part of the complement pathway, a cascade of proteins that leads to phagocytosis and breakdown of pathogens and signaling that strengthens the adaptive immune system. Component C2 is part of the classical, lectin and GZMK complement systems. [Serine protease complement C2b]: Catalytic component of the complement C3 and C5 convertase complexes. Following complement activation, recruited to the surface of pathogens by complement C4b opsonin to form the C3 convertase, or C3b and C4b opsonins to form the C5 convertase. As part of the C3 convertase, cleaves and activate C3 into C3a anaphylatoxin and C3b opsonin, the next components of the complement pathways. As part of the C5 convertase, cleaves and activate C5 into C5a anaphylatoxin and C5b component of the membrane attack complex.
Synonyms: ARMD14; CO2
Tractability: Small molecule: a structure with a bound ligand is known; it has a binding pocket of medium quality. Antibody: UniProt places it where antibodies can reach, with high confidence; its Gene Ontology location is reachable by antibodies, with high confidence; UniProt predicts a signal peptide or a membrane-spanning region. PROTAC: a small molecule that binds it is known.
Target class: Enzyme; Hydrolase
Gene: Protein-coding gene on chromosome 6 (31,897,785 to 31,945,674, forward strand). Ensembl gene ENSG00000166278.
Subcellular location: Secreted; Cell surface
Pathways (Reactome):
Immune System: Activation of C3 and C5; Initial triggering of complement; Regulation of Complement cascade
Gene Ontology:
Molecular function: protein binding; serine-type endopeptidase activity
Biological process: complement activation; complement activation, GZMK pathway; positive regulation of apoptotic cell clearance; complement activation, classical pathway; response to bacterium; innate immune response; proteolysis
Cellular component: cell surface; extracellular exosome; symbiont cell surface; extracellular region
Genetic constraint (gnomAD): Loss-of-function variants: 64 observed, 86.72 expected, observed/expected ratio (o/e) 0.74, 90% interval 0.6 to 0.91. The synonymous counts are far from expectation, so gnomAD's model fits this gene poorly and the ratio says little. Missense variants: 820 observed, 1,022.3 expected, observed/expected ratio (o/e) 0.8, 90% interval 0.76 to 0.85. Synonymous variants: 310 observed, 391.27 expected, observed/expected ratio (o/e) 0.79, 90% interval 0.72 to 0.87.
Homologues: Orthologues: pig C2 (83% identical), dog C2 (83% identical), rabbit C2 (81% identical), rat C2 (77% identical), mouse C2 (76% identical), guinea pig C2 (75% identical). Paralogues in human: CFB (39% identical), CSMD2 (16% identical), CSMD1 (16% identical), CSMD3 (16% identical), SEZ6L (15% identical), SEZ6L2 (15% identical), SEZ6 (15% identical), SVEP1 (13% identical), CR1 (11% identical), CR2 (10% identical), CFH (8% identical), PAPPA2 (7% identical), and 27 more.
Diseases named in the same sentence as C2 in open-access papers:
C2 is named in the same sentence as 159 diseases in open-access papers, as found by Europe PMC text mining. Sharing a sentence is not in itself a finding about the gene and the disease. The quoted sentences say what the papers report.
systemic lupus erythematosus (34 papers, 2010 to 2025). An autoimmune multi-organ disease typically associated with vasculopathy and autoantibody production. "In particular, complete genetic deficiency of complement component C2 is a strong risk factor for monogenic systemic lupus erythematosus (SLE), and partial deficiencies of C2 and C4A are important risk factors for SLE and primary Sjögren’s syndrome." (PMID 40142826, 2025). "Early-onset SLE or lupus-like phenotypes have been associated with the deficiency of complement factors, including C1q, C1r, C1s, C2, C3, C4A, and C4B." (PMID 39660463, 2025). "Heterozygous C2 variations in combination with variants in other complement genes (C4 and C8) have been reported to increase the risk of autoimmune diseases such as systemic lupus erythematosus." (PMID 41188636, 2025). "For example, only 10–30% of people with damaging mutations in the gene encoding complement component 2 (C2) develop systemic lupus erythematosus (lupus)." (PMID 36585519, 2023). "Genetic deficiencies in early components of complement (C1, C4, and C2) increase the risk of development of the ADs systemic lupus erythematosus (SLE) and glomerulonephritis (GN), presumably because of a decrease in these protective complement mechanisms." (PMID 32514272, 2020). "Paradoxically, patients with homozygous deficiency of the CP components, including C1 (C1q, C1r, or C1s), C4, or C2, have a high risk of lupus or lupus-like disease." (PMID 29892304, 2018). "C2 is the most common complement deficiency, occurring in about 1 in 20,000 individuals of European descent, however lupus develops only in about 10% of patients with C2 deficiency." (PMID 30459768, 2018). "For example, deficiencies of C1q,r,s, C4, and C2 are associated with systemic lupus erythematosus (SLE)-like disease, reflecting the important role of the classical complement pathway in clearance of immune complexes from the body." (PMID 25646095, 2014). "C1, C2, C3, C4 deficiency and increased levels of C3d (resulting from the breakdown of C3) are associated with Lupus." (PMID 24116013, 2013). "Deficiencies of the early complement components, C1, C2, and C4, are inherited in an autosomal recessive manner and classically associated with autoimmune diseases, particularly systemic lupus erythematosus (SLE), although the impact on Nm infection is controversial." (PMID 32067109, 2020). "Therefore, deficiencies of C1q, C1r, C1s, C2, or C4 have been strongly associated with both immunodeficiency as well as autoimmunity, including lupus-like phenotype." (PMID 30459768, 2018). "In systemic lupus erythematosus (SLE), for instance, complement deficiencies in components like C1q, C4, and C2 impair the clearance of immune complexes, leading to immune dysregulation and chronic inflammation." (PMID 39684535, 2024). "C1q, C4, and C2 deficiency significantly increases the risk of developing systemic lupus erythematosus (SLE) through mechanisms including faulty apoptotic material clearance." (PMID 35955822, 2022). "Individuals deficient in the C1 complex, C4 and to a lesser degree C2 are likely to suffer from severe bacterial infections and systemic lupus erythematosus (SLE)." (PMID 21085669, 2010). "In two of 14 patients with systemic lupus erythematosus (SLE) and GN, a heterozygous pathogenic variant (c.841_849 + 19del) in the C2 gene was detected." (PMID 41019761, 2025). "Classical pathway defects (e.g., C1q, C2, and C4) are linked to recurrent infections by encapsulated bacteria (Streptococcus pneumoniae and Haemophilus influenzae) and autoimmune disorders like systemic lupus erythematosus (SLE)." (PMID 40005649, 2025). "The role of the complement cascade in LN is well evidenced; deficiencies in components of the complement cascade can lead to monogenic lupus (C1q, C2 and C4) and low levels of C3 and C4 are assessed in the clinic to monitor disease activity." (PMID 32605540, 2020).
systemic lupus erythematosus (continued). "Genetic deficiencies in CP components C1q, C4 and C2 strongly associate with the autoimmune disease systemic lupus erythematosus (SLE), that may be caused by the failure of macrophages to phagocytose apoptotic cells." (PMID 32849513, 2020). "Cluster 5 contains classical complement pathway, classical antibody-mediated complement activation, pertussis, complement activation, oxidative damage, systemic lupus erythematosus, initial triggering of complement, and creation of C4 and C2 activators." (PMID 31739287, 2019). "Lupus-prone families with primary defects of classical complement pathways (C1q, C1r/s, C2, C4A and C4B) revealed the importance of this pathway for lupus pathogenesis." (PMID 30744169, 2019). "Among the strongest, known genetic risk factors for the development of systemic lupus erythematosus (SLE) are deficiencies of the classical complement pathway components (C1q, C1r, C1s, C4, or C2)." (PMID 25688346, 2015). "Deficiencies of complement components of the classical activation pathway, C1, C2 and C4, all lead to increased susceptibility to bacterial infections and increased risk of developing autoimmune disease, particularly systemic lupus erythematosus (SLE)." (PMID 20727163, 2010). "On the other hand, disruption of the complement process may result in the development of autoimmunity, and some chronic inflammatory diseases are also linked to C2 polymorphisms and deficiencies: both systemic lupus erythematosus (SLE) and age-related macular degeneration." (PMID 38892429, 2024). "Moreover, some defects of complement pathway gene products, including C2, C3, C4 and C1q, play an important role in the pathogenesis of lupus." (PMID 34150746, 2021). "While C1q deficiency results in development of lupus in virtually all cases, absence of C3, C2, and C4 results in lupus at lower frequency indicating a role for C1q beyond classical complement pathway activation in regulation of the immune response." (PMID 25191325, 2014). "Thus, in a cohort of 117 paediatric lupus cases (<16 y, median age 9 y) in which 20% had familial SLE, drawn from Europe, Asia and Africa, a diagnostic yield of 7% (eight moFL cases) were identified (C1QA, C1QC, C2, DNAS1L3, IKZF1)." (PMID 40465409, 2025). "It is associated with common type I C2 deficiency and certain autoimmune diseases (e.g., systemic lupus erythematosus), but its effect on AMD has not been reported to date, although the C2 itself is connected to the AMD phenotype." (PMID 36615095, 2022).
COVID-19 (16 papers, 2021 to 2025). A disease caused by infection with severe acute respiratory syndrome coronavirus 2. "Nonetheless, the reduced KIR3DL1/Bw4 pairs in severe patients and increased KIR2DL1/C2 pairs in mild patients indicate that the potency of NK cell education influences COVID-19 vulnerability." (PMID 36849422, 2023). "Children with convalescent COVID-19 had significantly elevated levels of C1q, C2, C3, C3b/iC3b, C4b, C5, C5a, and MBL complement proteins and of complement regulatory proteins like factor B and factor H in comparison with children in the control group." (PMID 36961465, 2023). "Children with acute COVID-19 had significantly elevated levels of C1q, C2, C4, C3, C5, C5a, C3b, factor B, factor H, and factor I in comparison with convalescent COVID-19 children." (PMID 36961465, 2023). "We similarly showed that pregnant participants with severe COVID-19 had upregulation of C3/C5 convertase, complement component C2, complement component C9, and complement C1q subcomponent subunit C, indicating increased complement activation." (PMID 36383608, 2022). "Children with acute COVID-19 also had significantly elevated levels of C1q, C2, C4, C3, C5, C3b/iC3b, C4b, C5a, and MBL complement proteins and of complement regulatory proteins like factor B, factor D, factor H, and factor I in comparison with control children (eTable 2 in Supplement 1)." (PMID 36961465, 2023). "Upregulation of C1s (1.60-fold), C1q (1.53-fold), C2 (2.76-fold), C3 (1.9-fold), and C4b (2.45-fold) indicated that timely complement activation may contribute to COVID-19 in CMs." (PMID 35903092, 2022). "Concurrent with the existing studies, we observed elevated levels of complement pathways components (C1q, C2, and C4) in children with MIS-C and acute COVID-19." (PMID 36961465, 2023). "The complement proteins C1q, C2, C4, C4b, MBL, C5, C5a, C3, C3b and complement factors such as factor B, factor D, factor H, and factor I were significantly enhanced in children with severe or moderate COVID-19 (eFigure 3, eTable 5, eTable 6 in Supplement 1)." (PMID 36961465, 2023). "We found levels of the complement component 2 (C2, protein ID P06681) and complement component 9 (C9, Protein ID P02748) proteins were elevated in the severe and non-severe COVID-19 groups as compared to the healthy group." (PMID 35842456, 2022). "Similarly, in previous reports, FGB, FGG, complements C4, C3, C5, C2, C9, and complement C1q subcomponent subunits A, B, and C (C1QA, C1QB and C1QC) were found to be upregulated in the lung tissues of patient with COVID-19." (PMID 38882332, 2024). "Therefore, we compared the admission (pretreatment) plasma levels of C1q, C2, C4, C4b, MBL, C5, C5a, C3, C3b, factor B, factor D, factor H, and factor I between children with COVID-19 who developed moderate or severe disease and those who developed only mild disease." (PMID 36961465, 2023). "Among KIR/HLA-C pairs, inhibitory KIR2DL1 binds to C2 with higher affinity than KIR2DL2/3 to C1, which may account for the increased KIR2DL1 + C2 combination in mild, but not severe COVID-19 patients." (PMID 36849422, 2023). "Concentrations of select chemokines (CXCL8, CXCL10, CCL2, CCL3, CCR1) and complement factors (C2, C9, CFD, C4BPA, C5AR1, CR1) were examined at mRNA and protein levels with regard to a COVID-19 course (ICU vs. non-ICU group) and CMV status at different time intervals." (PMID 36232655, 2022).
age-related macular degeneration (12 papers, 2007 to 2024). Age-related loss of vision in the central portion of the retina (macula), secondary to retinal degeneration. "Some autoimmune diseases have been linked to C2 deficiency, and SNPs in C2 have been connected to altered susceptibility to age-related macular degeneration." (PMID 38473271, 2024). "Many C2 variants has been associated with Age-related Macular Degeneration (AMD)." (PMID 38956727, 2024). "For example, in age-related macular degeneration (AMD), a retinal disease clinically and pathologically linked to LOAD, genes encoding complement components C2, C3, FB and C9, and regulators FH and FHR4, all contribute to risk." (PMID 33804666, 2021). "Indeed, genes in the complement pathway, including complement factor H (CFH), C2/BF, and C3, are known to be associated with age-related macular degeneration (AMD)." (PMID 27748412, 2016). "Although the inflammation in AMD is largely mediated through complement-associated pathways, such as CFH, CFI, C2, CFB, and C3, other mechanisms have also been reported, including age-related maculopathy susceptibility (ARMS2), which acts through a matrix metalloproteinase inhibitor." (PMID 36011777, 2022). "The CD subtype of AMD was significantly associated with current smoking as well as variants in the complement factor H (CFH), age-related maculopathy susceptibility 2 (ARMS2), complement factor B/complement component 2 (CFB/C2), complement component 3 (C3), and apolipoprotein E (APOE) genes." (PMID 22933840, 2012). "In genetic studies on age-related macular degeneration (AMD), its association with the CFH gene led to the discovery that other molecules in the complement pathway were also associated with the condition, such as C2/CFB, C3, and CFI." (PMID 23213273, 2012). "Recent findings that variants in complement factor H, B, complement component 2 (C2), and LOC387715/HTRA1 genes may increase the risk to develop age-related macular degeneration (AMD) provide insight into the pathological process of AMD." (PMID 17615538, 2007).
autoimmune disease (11 papers, 2015 to 2025). A disorder resulting from loss of function or tissue destruction of an organ or multiple organs, arising from humoral or cellular immune responses of the individual to their own tissue constituents. "Reduced complement C2 may reflect the activation-associated consumption of the complement system, a common finding in autoimmune diseases." (PMID 40142826, 2025). "HAE patients often have reduced C2 and C4 complement components, leading to decreased immunocomplex solubilisation but also polyclonal B-cell activation, which may predispose them to autoimmune diseases." (PMID 31236065, 2019). "Gene variants at the TSBP1-AS locus are strongly associated with the levels of complement component 4 (C4), C2/LILRB4 protein level ratio, IGA glomerulonephritis, BMI, lipoprotein levels, and with many autoimmune diseases including celiac disease (GWAS catalog)." (PMID 40883722, 2025). "However, the role of complement in the etiopathogenesis of autoimmune diseases is manifold as the complement components C1q, C2, and C4 contribute to the clearance of postapoptotic, secondary necrotic cells and their deficiency is, therefore, a risk factor for autoimmunity and autoinflammation." (PMID 26185769, 2015).
complement deficiencies (9 papers, 2017 to 2025). "It should be noted that even at the 19th month, control classical pathway deficiency was observed, raising the suspicion of complement deficiency (in other than the C2 gene) or a functional interaction between the remaining paraproteins and complement." (PMID 41226350, 2025). "At 19 months, both the classic pathway and the MBL lectin pathways appeared to be deficient again, raising the possibility of C2 complement deficiency (the most frequent cause of classical pathway deficiency in Central Europe)." (PMID 41226350, 2025). "Monogenic SLE was first described in the 1970s and found to be caused by early complement deficiencies (C1q, C1r/C1s, C2, and C4)." (PMID 37622085, 2023). "Primary complement deficiencies in this cohort included C1q deficiency (n = 3), C2 deficiency (n = 11), C6 deficiency (n = 3), and C8 deficiency (n = 1)." (PMID 32972440, 2020). "Heterozygous GOF mutations in C3 are now added to the list of genetic complement deficiencies causing vasculitis such as C1q, C1r, and C1s deficiency, complement factor I deficiency and complement C2 and C4 deficiency." (PMID 30443255, 2018). "There was a strong association between C2 complement deficiency and CLE." (PMID 35721085, 2022). "The most frequent complement deficiencies affect C2 and MBL, which often remain clinically silent." (PMID 34434189, 2021). "In SLE, 30% of the patients have a preexisting complement deficiency (preferentially of C4, C2, and C1), and deficiencies (preferentially of C5–C9 and properdin) are estimated to occur in up to 20% of individuals suffering from disseminated Neisseria infections." (PMID 34434189, 2021). "Different studies observed the association of SLE with Human Leukocyte Antigen (HLA) class 2 antigens (HLA-DR2 and DR3) in both white and black ethnicities; as well as with hereditary diseases due to complement deficiency: C1r, C1s, C1, INH, C4, C2, C5, and C8, mainly with C2 lack." (PMID 36059466, 2022).
Autoimmunity (8 papers, 2007 to 2024). The occurrence of an immune reaction against the organism's own cells or tissues. "Deficiency of C2 leads to autoimmunity, and C2 protein participates in both the classical and lectin pathways of the complement cascade, though C2 is not required for activation of the complement system by the classical or lectin pathway." (PMID 35069847, 2022). "Deficiency of early components of the classical pathway (C1, C2 and C4) leads to autoimmunity whereas deficiency of C3 and its regulators has been associated with severe recurrent bacterial infections and autoimmunity." (PMID 34362117, 2021). "C1INH-HAE could produce autoimmunity due to the consumption of early components of the classical complement pathway, as in patients with genetic C1 or C2 deficiencies." (PMID 36186797, 2022). "The complement system also plays a crucial role in SLE pathogenesis, particularly components such as C1QA, C1QB, C2, and C3, which are essential for clearing apoptotic debris and immune complexes, thereby reducing autoimmunity and systemic inflammation." (PMID 39717551, 2024). "It therefore seems more probable that the development of autoimmunity in MRL mice is in part related to a functional deficiency in C4, similar to that seen in humans with deficiencies in early classical pathway components such as C1q, C2, and C4." (PMID 17971229, 2007).